IL6 (interleukin 6)
Diseases named in the same sentence as IL6 in open-access papers (continued):
Sharing a sentence is not in itself a finding about the gene and the disease.
Sepsis (continued). "D-gal also worsens cecal ligation and puncture (CLP) sepsis severity when compared with PBS-CLP mice, as indicated by serum creatinine (Scr) and alanine transaminase (ALT), but not mortality, neurological characteristics (SHIRPA score), and serum cytokines (TNF-α and IL-6)." (PMID 39423218, 2024). "The lipopolysaccharide infusion induced sepsis-like inflammation with tachycardia, elevated pulmonary pressure, elevated lactate level, as well as elevated pro-inflammatory cytokines like interferon (IFN)-γ, interleukin (IL)-1β, IL-2, IL-6, IL-8, IL-12 and tumor necrosis factor alpha (TNF-α)." (PMID 39273234, 2024). "Thus, this study indicates that metformin, by regulating the AMPK/SIRT1/PGC-1α pathway, could reduce reactive oxygen species and inflammatory cytokines (IL-1β, IL-6, IL-8, and TNF-α) in a mouse model of sepsis." (PMID 38791227, 2024). "RBC-bound microbial DNA community richness but not DNA burden correlates with IL-6 in human sepsis." (PMID 39666381, 2024). "In sepsis, the mitogen-activated protein kinase (MAPK) pathway is consistently activated in conjunction with the NF-κB pathway, either independently or cooperatively stimulating the secretion of downstream inflammatory factors such as COX-2, TNF-α, IL-1β, IL-18, IL-6, and iNOS." (PMID 39267971, 2024). "However, plasma apoA-IV levels did not correlate with CRP, procalcitonin and IL-6, and our analysis does not provide evidence for an anti-inflammatory effect of apoA-IV in sepsis." (PMID 39311203, 2024). "After sepsis induction, mortality rates, degree of hypothermia, and plasma IL-6 levels, a marker of acute systemic inflammation, were all equivalent in TG and WT mice of both sexes, confirming that MnSOD overexpression does not alter overall sepsis severity." (PMID 39563237, 2024). "Furthermore, IL-6-knockout mice do not demonstrate enhanced survival upon the induction of sepsis by cecal ligation and puncture, adding to the debate about the dual role of IL-6 in sepsis dynamics." (PMID 39056754, 2024). "As CRP—as marker of inflammation and IL-6 activity—is a potential confounder, and inclusion of CRP in models could lead to collider bias, we re-ran our primary analyses (on sepsis incidence, sepsis-related mortality, and sepsis-related death) with and without adjusting for CRP." (PMID 37814277, 2023). "In the course of sepsis, DCs first transfer to the antigen epitopes of neutrophils, macrophages, and T helper lymphocytes (Th), activate NF-κB, enter the nucleus and form a complex with DNA, induce cell apoptosis, and release numerous proinflammatory cytokines and chemokines, such as TNF-α and IL-6." (PMID 36816800, 2023). "Therefore, it suggested that SIN might protect against sepsis-induced MI via targeting TNF-α, IL-6, and IL-1β." (PMID 37388447, 2023). "To determine whether Erbin-mediated autophagy regulates sepsis-induced inflammatory response and organ injury, we investigated the level of inflammatory cytokines TNF-α, IL-6, IL-1β, HMGB1, and IL-10 in polymicrobial sepsis mice and MDP-treated BMDMs with CQ treatment." (PMID 38105228, 2023). "In particular, IL-6 modulation by PMX-DHP can be enhanced with using CHDF, which may suggest that the current combination treatment can maintain not only early stage of sepsis but also late phase of sepsis via some cytokine cascade." (PMID 37007795, 2023). "In addition, the secretion of IL-6 and IL-1β by PGN-stimulated DCs may contribute to sepsis pathology when bacteria and PGN reach high levels in the blood or tissues." (PMID 36677464, 2023). "In the process of sepsis, cytokines such as TNF-α, IL-1β, and IL-6 mediated inflammatory response plays an important role, which may lead to endothelial and epithelial damage, affect vascular permeability and heart function, and eventually result in tissue necrosis and organ failure." (PMID 38152336, 2023).
Sepsis (continued). "Interestingly, we found that the Peli1 global knockout group showed more IL-6 released in the blood stream when compared to the WTCLP (706.8 ± 43 vs. 483.2 ± 24.01; pg/mL; n = 6; p < 0.0001) and CP1KO sepsis groups (706.8 ± 43 vs. 503.3 ± 10.59; pg/mL; n = 6; p = 0.0002)." (PMID 37296648, 2023). "Here, after the induction of sepsis, IL-10 levels were attenuated in OSMR KO mice following the induction of FIP, as were the levels of the pro-inflammatory cytokines IL1β, IL-6, TNF, and KC, which may reflect a more balanced attenuation of inflammation with improved survival." (PMID 36831019, 2023). "In comparison to the sham group, the sepsis group had significantly higher levels of TLR-4, IL-6, TNF-α, MIF, F2-isoprostane, caspase-3, cTn-I, and CK-MB, while the pre-treated group with Xanthohumol had significantly lower levels (p<0.05) of these markers than the sepsis group." (PMID 37900069, 2023). "The disruption of TLR4 alone markedly reduced the pCTS-L–induced secretion of most cytokines (e.g., IL-6 and IL-12) and chemokines (e.g., RANTES, MCP-1, MIP-1γ, and LIX) except for MIP-2/GRO-β and KC/GRO-α, two neutrophilic surrogate markers of experimental sepsis." (PMID 36735789, 2023). "Finally, of particular interest is the observation that elevation of IL-6 seen in our post-COVID cohort, and reported by others, is not specific to post-COVID but is also seen in a post-sepsis cohort." (PMID 36844209, 2023). "Further investigations into the specificity and sensitivity of IL-6 could not be carried out due to the limited sample size of sepsis cases in 2022." (PMID 38255366, 2023). "In addition, the DC production of pro-inflammatory IL-6 and IL-1β upon PGN stimulation could exacerbate the inflammatory sepsis pathology in instances when the bacteria and PGN reach high levels in the blood or tissues." (PMID 36677464, 2023). "We conducted a systematic review a systematic review and meta-analysis to determine, in critically ill adults with sepsis, whether procalcitonin (PCT), C-reactive protein (CRP), interleukin-6 (IL-6), and presepsin (sCD14) are independent prognostic factors for mortality." (PMID 37537680, 2023). "While proinflammatory cytokines and chemokines, such as IL-6, TNFα, MCP-1, and IL-8, peak between 2–4 h after the introduction of inflammatory stimuli, SAA expression in plasma peaks at ~48 h after the induction of sepsis during the resolution phase of acute inflammation." (PMID 38139330, 2023). "In our study, we found that injecting parenteral ω-3 PUFA solutions reduced IL-1β, TNF-α, IL-6, IL-10, IFN-γ, and IL-17 levels and hindered the secretion of multi-organ injury markers induced by CLP treatment, indicating the protective role of ω-3 PUFAs in sepsis." (PMID 36694426, 2023). "Indeed, in the setting of Gram-negative bacteremia and sepsis, the onset of myocardial depression and ventricular dilatation following an outflow of cytokines (IL1β, IL-6, and TNFα), nitric oxide, and endotoxins has been reported." (PMID 37756092, 2023). "Furthermore, Ticagrelor was found to reduce tissue cytokine levels of the lung (IL-1, TNF a, IL-6, F2 isoprostane, GPR 17, MIF) in male mice during CLP-induced polymicrobial sepsis by modulation of pro-inflammatory and oxidative stress cascade signaling pathways." (PMID 37675176, 2023). "IL-6 showed a low value of AUROC among sepsis patients, suggesting that it may not be as useful as other markers in predicting patient outcomes." (PMID 37510189, 2023). "Mean serum interleukin-6 values of patients who never had increased laboratory parameters of infection nor died during their stay and mean interleukin-6 values on the day of blood sampling for a later positive culture in patients with culture-confirmed sepsis were analysed for each time period." (PMID 36216867, 2023).
Sepsis (continued). "Patients suspected of having sepsis underwent a Sequential Organ Failure Assessment (SOFA) evaluation and had blood drawn for blood cultures, complete peripheral blood counts (CBC), and measurements of various markers such as C-reactive protein (CRP), procalcitonin (PCT), and interleukin-6 (IL-6)." (PMID 37510189, 2023). "However, the limitation of IL-6’s short half-life, especially for patients not admitted on the first day of sepsis, can be mitigated through the complementary consideration of CRP levels." (PMID 38255366, 2023). "Likewise, administration of the MGMT inhibitor in LPS-activated wild-type (WT) macrophages also demonstrated anti-inflammatory effects through these parameters (except for supernatant IL-6), suggesting a possible use of MGMT inhibitor to attenuate sepsis-induced hyperinflammation." (PMID 37373325, 2023). "However, in sepsis, global blockage of classic IL6 signaling and trans-signaling via IL6-R Mab application was not beneficial, while only selective inhibition of IL6 trans-signaling was." (PMID 36151360, 2023). "ROC curve analysis revealed C1INH expression could differentiate between cohorts with/without subsequent development of sepsis, and the discrimination ability was enhanced when combined with circulatory IL-6 and CRP levels (AUC = 0.926, 95%CI = 0.87-0.97)." (PMID 35669402, 2022). "In our previous research of multi-organ dysfunction syndrome in LPS-induced sepsis, we have shown that simvastatin pretreatment improved survival and significantly suppressed the over-production of pro-inflammatory cytokines, TNF-α, and interleukin (IL)-1β and IL-6." (PMID 35269738, 2022). "Our study showed that P-SEP may be a useful biomarker in prompt detection of early-onset sepsis in late preterm and term newborns, however it's not individually superior to IL-6." (PMID 36699313, 2022). "As a result, we could not make any statements concerning sgp130, sIL-6R, and IL-6 serum concentrations in patients with postoperative complications, such as sepsis or serious infections." (PMID 35160042, 2022). "Additionally, significantly higher IL6 levels were observed in sepsis trauma patients when compared to their non-septic counterparts (p < 0.0001)." (PMID 36471343, 2022). "MiR-451a was positively associated with TNF-α (rs = 0.206, p = 0.026), IL-1β (rs = 0.209, p = 0.023), CRP (rs = 0.328, p < 0.001), and the APACHE II score (rs = 0.272, p = 0.003), while it did not relate to IL-6 (rs = 0.141, p = 0.129) in the patients with sepsis." (PMID 35992658, 2022). "This supports the hypothesis that the discriminating power of IL-6 and IL-10 for G-/G+ sepsis is independent of the site of infection (bloodstream or non-bloodstream infection)." (PMID 36544765, 2022). "While in patients without progressive organ failure, IL-6 and IL-10 levels were still significantly elevated after G- bacterial infection, proving the comparable G+/G- bacteria discriminating power in non-severe sepsis." (PMID 36544765, 2022). "LP17 has also been shown to be an effective treatment for sepsis secondary to Pseudomonas aeruginosa pneumonia in rats, resulting in with improved hemodynamic status, attenuated lactic acidosis and hypoxemia, reduced serum TNF-α, IL-1β, and IL-6, and improved 7-day survival of the septic rats." (PMID 35784361, 2022). "The silencing of miR-10a can inhibit sepsis-induced liver injury in rats, suggesting a possible protective role, with the downregulation of the TGF-β1/Smad pathway and the inhibition of the expression of IL-6, ROS and TNF controlling inflammatory development in septic rats." (PMID 36012630, 2022). "However, there have been no direct reports indicating that the removal of IL-6 or HMGB-1 improved sepsis mortality." (PMID 36005726, 2022).
Sepsis (continued). "A recent analysis of 480 episodes of suspected LOS in 208 preterm infants below 32 weeks of gestational age showed that serum IL-6 and PCT levels (hazard ratios 2.28 and 2.91, respectively), but not CRP (hazard ratio 1.16), were associated with sepsis severity and mortality risk." (PMID 35345614, 2022). "The mice sepsis model is established using lipopolysaccharide (LPS) injection, and the expression levels of proinflammatory cytokines, such as tumor necrosis factor alpha (TNF-α), interleukin-6 (IL-6), and interleukin-10 (IL-10) in both RAW246.7 cells and lung tissues, are tested." (PMID 35814267, 2022). "Similar results were shown in models of acute lung injury after sepsis (decreased TNF-α, IL-1β, and IL-6 secretion) and paraformaldehyde injury (decreased cell death, MyeloPeroxidase activity, parenchymal vascular permeability, TNF-α and IL-6 secretion, and increased IL-10 secretion)." (PMID 35874678, 2022). "6-Gingerol-treated mice also displayed lower mortality in polymicrobial sepsis induced by CLP by enhancing bacterial clearance in the peritoneum, blood, and organs (liver, spleen, and kidney) while also suppressing the generation of TNF-α and IL-6 in TLR2 and/or TLR4-stimulated macrophages." (PMID 36588685, 2022). "Besides, the serum levels of TNF-α, IL-1β, and IL-6 in the γ3-RBCNPs group were significantly lower than those in PBS groups, indicating that γ3-RBCNPs reduced systemic inflammatory response in mice with sepsis." (PMID 35783411, 2022). "However, data regarding the therapeutic effects of triple cytokine (TNF-α, IL-1β, and IL-6) inhibitions versus single cytokine (TNF-α) inhibition against sepsis remain lacking." (PMID 35337084, 2022). "In addition, our study showed that the plasma RIP3 levels were significantly positively correlated with postoperative inflammatory cytokines such as PCT and IL-6, a finding that was consistent with a study showing a positive correlation between the plasma RIP3 and PCT levels in sepsis patients." (PMID 35292064, 2022). "IL-6, which stimulates acute phase proteins including serum amyloid A, and has been previously demonstrated to displace up to 45% of ApoA-I from circulating HDL-C in sepsis was also elevated, and may contribute to Dys-HDL pathogenesis." (PMID 34535154, 2021). "While the underweight group showed a consistent significance as an independent predictor for 28-day mortality with either of IL-6 levels, only IL-6 levels at day3, but not IL-6 levels at day1 and day2, was a significant variable for predicting the outcome during sepsis." (PMID 33452302, 2021). "Moreover, IL-6 showed a high negative predictive value on day 1 (close to 89%) to exclude bacteremia/sepsis." (PMID 34828740, 2021). "In addition to IL-6, early proinflammatory cytokines, such as TNF-α, IL-1, and IL-8 were studied to determine if their levels correlated with mortality from sepsis and septic shock, which are traditionally considered a consequence of an exacerbated early innate immune response." (PMID 33803628, 2021). "Furthermore, in a mice model of sepsis-induced by caecal ligation and puncture, the non-survivor mice have a significant increase of interleukin-6 (IL-6), interleukin-1β (IL-1β), and tumour necrosis factor-α (TNFα) in adrenal protein extracts." (PMID 33571577, 2021). "Sepsis induction reduced NF-κB and SOD2 protein expression but increased their acetylation, and this was accompanied by an increase in proinflammatory cytokines (TNF-α/IL-6/IL-10) and oxidative stress (indicated by reduced SOD2 activity, GSH content, GSH/GSSG ratio, and CAT activity)." (PMID 33790896, 2021). "In the early stage of sepsis, to eliminate invading bacteria, macrophages are activated to become the M1 type, which produces a large number of proinflammatory factors, such as tumour necrosis factor (TNF)-α, interleukin (IL)-6, IL-1β, type I interferon, and chemokines." (PMID 34627385, 2021). "CLP-induced sepsis resulted in increased Il6, Ltf, and Lbp but not Tnf in BAT." (PMID 34322037, 2021).
Sepsis (continued). "The IL‐6 inhibitor tocliziumab has been used successfully in cytokine release syndrome following chimeric antigen receptor T‐cell therapy (CAR‐T), and IL‐1 blockade with anakinra has proven beneficial in patients with a hyperinflammatory state secondary to sepsis." (PMID 35846103, 2021). "Our findings also suggest that the optimal combination of INR, NT-proBNP and IL-6 has a significantly higher AUC value than that of conventional scoring systems such as SOFA and APACHEII scores, and provides need to confirm its validity for screening sepsis-related mortality." (PMID 33446739, 2021). "However, an in vivo study suggested that knocking out IL6 in mice was not shown recovery from sepsis owing to the role of IL6 in host defense mechanism from pathogens and tissue damage." (PMID 35126382, 2021). "However, the elevation in IL-6 was not to the same degree as it was seen in the other sepsis models." (PMID 34702761, 2021). "Our findings agree with results from a small case-control study in Egyptian children with sepsis (n = 40, mean age 6 years) and a large community-based study of children (n = 4274, mean age 9.9 years) in England, which reported that 25(OH)D levels increased with increasing levels of CRP and IL-6." (PMID 34011341, 2021). "Inhibitors of IL-6 and its receptors, such as Tocilizumab, have been approved by the FDA for treating chimeric antigen receptor (CAR)-T-cell mediated cytokine release syndrome (CRS), and have been proposed as a new therapeutic strategy for other types of cytokine wave including sepsis." (PMID 34960725, 2021). "We established both CLP- and LPS-induced sepsis models in mice and verified that SPION-MSCs significantly improved the symptoms of sepsis, such as increasing the survival rate of mice, reducing the levels of serum TNF-α, IL-6, ALT and AST, and relieving liver tissue damage." (PMID 34627385, 2021). "The Sepsis + ARDS group had a greater respiratory rate, a lower PaO2/FiO2, a greater SOFA score, and higher levels of lactate (LAC), procalcitonin (PCT), C-reactive protein (CRP), interleukin 6 (IL-6), tumor necrosis factor α (TNFα), IL-10, and FGF21 (all P < 0.05)." (PMID 34154595, 2021). "Additionally, we analyzed selected plasma cytokines (tumor necrosis factor (TNF)-α, Interferon (IFN)-γ, Interleukin (IL)-1β and IL-6) and bacterial infection burdens as well as changes in the peritoneal microbiome in experimental animals with CASP-induced sepsis." (PMID 33466819, 2021). "However, among the patients with sepsis, plasma IL-6 levels of the non-survivors were significantly higher than those of the survivors from day 1 to days 6-8, as were those of GDF-15 on days 2-3 and 6-8." (PMID 35095877, 2021). "In this study, we demonstrate the prognostic significance of several serological indicators such as IL-6, PCT, NT-proBNP, lactate, hepatorenal function, and coagulation function, to provide a clinical screening tool to identify and initiate early management of patients with sepsis." (PMID 33446739, 2021). "Additionally, sepsis severity in mice with subcutaneously implanted SE > CT catheters was more severe than in other groups as indicated by mortality rate, fungemia, serum cytokines (TNF-α and IL-6), and kidney and liver injury." (PMID 34746032, 2021). "However, the lack of changes in circulating IL-6 suggests that other mechanisms and tissues are involved and provide larger relative sources of cytokine secretion in this model of sepsis." (PMID 33795743, 2021). "Initially, sepsis was induced by performing CLP in mice, after which the mouse models presented significant myocardial depression, injury and inflammation, showing as decreased MAP, LVSP and ±dp/dtmax values, and increased cTnI, CK-MB, TNF-α, IL-6, IL-1β and NO levels in mice." (PMID 33645622, 2021).